TRA2B (transformer 2 beta homolog)
Diseases named in the same sentence as TRA2B in open-access papers (continued):
Sharing a sentence is not in itself a finding about the gene and the disease.
epilepsy (2 papers, 2025). A brain disorder characterized by episodes of abnormally increased neuronal discharge resulting in transient episodes of sensory or motor neurological dysfunction, or psychic dysfunction. "Gene variants in the human TRA2B gene that cause production of a dominant negative version of Tra2β protein cause a neurodevelopmental syndrome that includes microcephaly and epilepsy." (PMID 41178187, 2025). "In neurological disorders, aberrant isoforms of TRA2β have been linked to intellectual disability, epilepsy, and AD, via altered splicing of genes like CHEK1 and RAGE." (PMID 41009380, 2025).
glioma (2 papers, 2019 to 2020). A benign or malignant brain and spinal cord tumor that arises from glial cells (astrocytes, oligodendrocytes, ependymal cells). "Tra2β levels were greater in high-grade gliomas than low-grade gliomas, and Tra2β knockdown resulted in suppression of cell proliferation and inhibition of cell migration." (PMID 31311954, 2019).
viral infection (2 papers, 2021). "However, we identified multiple new TRA2B splice variants in the Cufflinks transcript assembly that displayed varying expression patterns during virus infection." (PMID 34960678, 2021). "The signal(s) that trigger alternative splicing of TRA2-β pre-mRNA during viral infection will be an intriguing avenue of investigation." (PMID 35127560, 2021). "Furthermore, the results suggest that TRA2-β can act as a key regulator of additional steps of the innate immune response to viral infection." (PMID 35127560, 2021).
and neck cancers (1 paper, 2023). "Elevated expression levels of TRA2B have been observed in several cancers, including lung, ovarian, cervical, stomach, head, and neck cancers, in which these elevated levels are associated with neoplasia and metastasis." (PMID 37547760, 2023).
astrocytoma (1 paper, 2023). "TRA2B seems implicated in astrocyte differentiation regulation specifically in astrocytoma." (PMID 37587118, 2023).
autoimmune disorders (1 paper, 2020). "In the context of autoimmune disorders, TRA2B has been included in a list of potential autoantigens in murine autoimmune kidney disease based on its affinity to dermatan sulfate." (PMID 32631453, 2020).
Azoospermia (1 paper, 2025). Absence of any measurable level of sperm,whereby spermatozoa cannot be observed even after centrifugation of the semen pellet. "Focussing on germ cell development, we found that Tra2b PE deletion causes azoospermia due to catastrophic cell death during meiotic prophase." (PMID 39748121, 2025).
glioblastoma (1 paper, 2025). The most malignant astrocytic tumor (WHO grade IV). "TRA2B’s implications in glioblastoma again highlight the therapeutic potential this protein has in the realm of cancer therapeutics." (PMID 41009380, 2025). "TRA2β also acts as a proto-oncogene in multiple cancers, including ovarian, squamous cell, and glioblastoma, where it promotes tumor growth and metastasis through splicing regulation of cell cycle and adhesion genes." (PMID 41009380, 2025).
heart failure (1 paper, 2017). Inability of the heart to pump blood at an adequate rate to meet tissue metabolic requirements. "Defects in the splicing factor that are pertinent to regulating cardiac-related genes such as hnRNP H, hnRNP U, RBM24 and tra2β are known to cause heart failure." (PMID 28077597, 2017).
Infertility (1 paper, 2025). "This indicated the small testis size and infertility of Tra2b-cPEko mice was caused by a block in germ cell development during meiosis." (PMID 39748121, 2025). "Creation of separate Tra2b-cPEko and Tra2b-cko mouse models using the same Vasa-Cre (active from E15, so causing deletion within embryonic germ cells from which all later stages of germ cell development arise) cause different infertility phenotypes." (PMID 39748121, 2025). "Female Tra2b-cko mice were also infertile, although these were not further analysed in this study (Fig. EV5D)." (PMID 39748121, 2025).
influenza (1 paper, 2014). An acute viral infection of the respiratory tract, occurring in isolated cases, in epidemics, or in pandemics; it is caused by serologically different strains of viruses (influenzaviruses) designated A, B, and C, has a 3-day incubation period, and usually lasts for 3 to 10 days. "With respect to influenza, expression of TRA2B protein was reported to be down-regulated in porcine alveolar macrophage cells infected by two swine IAVs." (PMID 25547032, 2014).
liver cancer (1 paper, 2013). An epithelial or non-epithelial malignant neoplasm that arises from the liver. "Tra2β protein is also known to interact directly with the RBMY protein which is implicated in liver cancer." (PMID 23935626, 2013).
lung adenocarcinoma (1 paper, 2013). A carcinoma that arises from the lung and is characterized by the presence of malignant glandular epithelial cells. "These genes include SMARCC1, TRA2B, CBX3 and PRPF6 that show the same upregulation pattern as EGFR in lung adenocarcinoma and we have reported all the mentioned genes for the first time in lung adenocarcinoma." (PMID 23874428, 2013).
Myotonia (1 paper, 2025). An involuntary and painless delay in the relaxation of skeletal muscle following contraction or electrical stimulation. "Interestingly, several splicing factors including Srsf6, Prpf39, Rbm7, Tra2b, Rbfox2, and Hnrnpu, exhibited alternative splicing in Mbnl1−/− mice with myotonia, but not in those without." (PMID 41000779, 2025).
Neurodevelopmental delay (1 paper, 2023). "In this study, we report a novel splice variant in the TRA2B gene identified in a patient presenting with seizures and neurodevelopmental delay." (PMID 37958557, 2023).
rheumatoid arthritis (1 paper, 2025). A chronic, systemic autoimmune disorder characterized by inflammation in the synovial membranes and articular surfaces. "Additionally, TRA2β modulates immune responses by controlling T cell differentiation and cytokine production and has been implicated in diseases such as HIV and rheumatoid arthritis." (PMID 41009380, 2025).
serous ovarian carcinoma (1 paper, 2023). "We assessed TRA2B expression in benign tissues, borderline ovarian tumor tissues, high-grade serous ovarian carcinoma (HSGOC) tissues and peritoneal metastatic tissue." (PMID 37547760, 2023).
squamous cell carcinoma (1 paper, 2025). A carcinoma arising from squamous epithelial cells. "TRA2β has been widely studied in cancer biology, with evidence supporting its role in the progression of multiple cancer types, including breast, cervical, ovarian, and colon cancer, and squamous cell carcinoma." (PMID 41009380, 2025).
tauopathies (1 paper, 2014). "Therefore, exploring upstream events leading to TRA2B upregulation may lead to insights on further reasons for the increase in 4R tau isoforms in some tauopathies." (PMID 25402454, 2014).
type 2 diabetes (1 paper, 2020). "The region on Chr C2 near SNPs 5 and 6, contained four known genes (TRA2B, CHCHD4, IGF2BP2 and SENP2) but none of these genes contained disease-associated protein-coding changes, despite TRA2B and IGF2BP2 having association with type 2 diabetes in other species." (PMID 33228033, 2020).
Ventriculomegaly (1 paper, 2014). An increase in size of the ventricular system of the brain. "In contrast, depletion of Tra2b in neuronal precursors leads to ventriculomegaly and aberrant cortical patterning." (PMID 24586484, 2014).
cancer (26 papers, 2012 to 2025). A tumor composed of atypical neoplastic, often pleomorphic cells that invade other tissues. "TRA2B-regulated AS was tightly associated with the mitotic cell cycle, apoptosis and several cancer pathways." (PMID 37547760, 2023). "We also found that TRA2B repressed the expression of genes associated with cell adhesion, suggesting that TRA2B contributes to cancer cell metastasis by changing the extracellular matrix composition." (PMID 37547760, 2023). "Some of the proteins which are known to interact either directly or indirectly with Tra2β have themselves been implicated with roles in cancer cells." (PMID 23935626, 2013). "The gene encoding this splicing factor is amplified in various types of cancer and the increased expression of Tra2β is associated with cancer cell survival." (PMID 24348561, 2013). "The TRA2B gene which encodes Tra2β becomes amplified in several cancers and particularly in cancers of the lung, cervix, head and neck, ovary, stomach, and uterus." (PMID 23935626, 2013). "Increases in TRA2B expression in human cancers can cause oncogenic patterns of splicing." (PMID 41178187, 2025). "The TRA2B gene is a transcriptional target of the protooncogene ETS-1 which might cause higher levels of expression in some cancer cells which express this transcription factor." (PMID 23935626, 2013). "Taken together, these observations suggest that the pathological mechanism of Tra2β upregulation in cancer cells might result from underlying changes in transcription factors in cancer cells." (PMID 23935626, 2013). "However, we do know that some of the known splicing targets of Tra2β identified in normal tissues are important for cancer cell biology and are particularly implicated in cell division and motility." (PMID 23935626, 2013). "The third known Tra2β-target exon which might be potentially relevant in cancer cells is in the HIPK3 gene, which encodes a serine/threonine kinase involved in transcriptional regulation and negative control of apoptosis." (PMID 23935626, 2013). "We discovered that a subset of cancer cell lines are unexpectedly vulnerable to loss of just TRA2A, despite having its partner TRA2B present." (PMID 40367120, 2025). "For instance, as mentioned in the introduction, KHSRP interacts with hnRNPA1, a protein known to resolve G4 structures at telomeres and in the promoters of genes such as KRAS and TRA2B, thereby modulating their transcription in cancer cells." (PMID 39763191, 2025). "CRISPR‐deletion of the TRA2B PE in human cancer cells increased both TRA2B expression and cell proliferation, indicating that normal intracellular levels of Tra2β protein are rate‐limiting for mitotic cell division." (PMID 41178187, 2025). "Vertebrates have two transformer 2 homologs, TRA2A and TRA2B, and there is emerging evidence that dysregulation of the human proteins is involved in abnormal patterns of splicing observed in some cancers." (PMID 40750357, 2025). "While loss of TRA2A alone is typically neutral due to compensation by TRA2B, we discover that a subset of cancer cell lines are highly TRA2A-dependent." (PMID 40367120, 2025). "The operation of the TRA2B PE in controlling the proliferation of activated T cells is similar to the picture of PE function developed from studies in cultured cancer cells." (PMID 41178187, 2025). "Several cancers, including breast, cervical, ovarian, and colon, show an increase in TRA2B protein levels." (PMID 38448406, 2024). "Several studies have revealed that TRA2B can inhibit cellular apoptosis or promote invasion in several cancers." (PMID 37547760, 2023). "Together, these results demonstrate the novel functional pathways through which TRA2B regulates the cell cycle in cancer cells." (PMID 37547760, 2023). "In this study, we used next-generation RNA sequencing (RNA-seq) to systematically investigate global TRA2B-regulated alternative splicing events (RASEs) and global gene expression changes after TRA2B silencing in cancer cells." (PMID 37547760, 2023).
cancer (continued). "Taken together, these results greatly expand the knowledge on the functions and molecular mechanisms of TRA2B in cancer." (PMID 37547760, 2023). "We discovered that mitotic cell cycle-related genes were significantly enriched among the TRA2B RASGs, providing an explanation for how TRA2B promotes cancer cell proliferation." (PMID 37547760, 2023). "In this study, we used a high-throughput transcriptome sequencing approach to explore the influence of TRA2B on global gene expression and AS in human cancer cells and validated the cancer-promoting functions of TRA2B in OC cells." (PMID 37547760, 2023). "In this study, we explored the molecular functions of a canonical RBP, Transformer 2β homolog (TRA2B), in cancer cells." (PMID 37547760, 2023). "It has recently been reported that TRA2B interacts with motif AAGG to promote cancer cell growth by disrupting gene expression processes associated with aging." (PMID 36923505, 2023). "Together, these results suggest that TRA2B knockdown in HeLa cells substantially regulates the expression of cancer-related genes." (PMID 37547760, 2023). "For example, Tra2-β was found to promote the occurrence of cancer by affecting the AS events of CD44." (PMID 35126520, 2022). "Reactive oxygen species made during inflammation provide a further potential mechanism for Tra2β upregulation in cancer cells." (PMID 23935626, 2013). "The second known splicing target of Tra2β with likely important functions in cancer cells is within the CD44 pre-mRNA." (PMID 23935626, 2013). "Three Tra2β-target exons have been identified in genes known to have important roles in cancer cells." (PMID 23935626, 2013). "Known Tra2β splicing targets have important roles in cancer cells, where they affect metastasis, proliferation, and cell survival." (PMID 23935626, 2013). "Upregulation of Tra2β protein expression has also been observed in several cancers, including breast, cervical and ovarian, and colon." (PMID 23935626, 2013). "Future analysis of the role of Tra2β in cancer cells will require the detailed identification of its endogenous splicing targets in cancer cells and the elucidation of their physiological roles." (PMID 23935626, 2013). "Here, we review these important principles for SRSF1 and then apply these principles to gauge the likely effect of the Tra2β protein on cancer-specific gene expression." (PMID 23935626, 2013). "As well as any potential role in cancer cells, Tra2β has important roles in normal development and is essential for normal mouse embryonic and brain development (TRA2B knockout mice fail to develop normally)." (PMID 23935626, 2013). "In this review, we particularly examine the potential role of the splicing regulator Tra2β as a modulator of gene function in cancer cells." (PMID 23935626, 2013). "The increased levels of Tra2β observed in cancer cells mean that the TRA2B gene must be able to bypass the normal feedback expression control mechanisms which exist to keep Tra2β protein levels under tight control." (PMID 23935626, 2013). "TRA2β expression usually promotes cancer metastasis and is usually lethal in these instances." (PMID 41009380, 2025). "In addition to its essential role in development, emerging evidence has shown that TRA2β is also widely involved in various diseases, particularly neurological disorders, cancer, and immune system dysfunctions." (PMID 41009380, 2025). "However, other data from cancer cells and transplanted T cells point more to a role for the TRA2B PE in controlling mitotic proliferation." (PMID 41178187, 2025). "Furthermore, we examine recent research uncovering TRA2β’s involvement in disease processes, particularly neurological disorders, cancers, and immune system dysfunction." (PMID 41009380, 2025). "TRA2B downregulation aligns with decreased cancer metastasis." (PMID 41009380, 2025).
cancer (continued). "Besides TRA2B gene amplification, increased levels of the ETS-1 and c-MYC transcription factors have been proposed as possible mechanisms to explain TRA2B upregulation in cancer cells." (PMID 38448406, 2024). "Interestingly, TRA2B knockdown also significantly influenced the AS pattern of TRA2B itself, implying the existence of a regulatory feedback loop involving TRA2B and its RNA targets in cancer cells." (PMID 37547760, 2023). "In summary, these results suggest that TRA2B extensively regulates ASEs in cancer cells." (PMID 37547760, 2023). "We validated the AS-regulating functions of TRA2B in OC patients and cancer cells." (PMID 37547760, 2023). "Both the TRA2B messenger RNA (mRNA) and Tra2β protein levels are increased in many cancers." (PMID 37547760, 2023). "Considering these results, TRA2B gene transcripts and hnRNPA1 or hnRNPU may be closely interacting regulators of the cell cycle or cell growth, which is a crucial phonotype of cancer cells." (PMID 31311954, 2019). "Here, we review the evidence that upregulation of the SR-related Tra2β protein might have a similar role in cancer cells." (PMID 23935626, 2013). "Tra2β is essential during embryonic development, and many embryonic developmental pathways involved in cell growth and motility which are turned off in adult cells often become reactivated in cancer cells." (PMID 23935626, 2013). "The splicing regulator Tra2β is upregulated in some human cancers." (PMID 23935626, 2013). "Interestingly, the Tra2β gene is a transcriptional target of the proto-oncogene ETS-1, whereas known Tra2β splicing targets play key roles in cancer cells, where they affect metastasis, proliferation, and cell survival." (PMID 24348561, 2013). "Tra2β protein expression has been demonstrated to be important for cancer cell biology." (PMID 23935626, 2013). "As well as TRA2B gene amplification, the expression levels of the ETS-1 transcription factor provide a possible mechanism through which Tra2β might be upregulated in cancer cells." (PMID 23935626, 2013). "Thus, paralogs involved in the regulation of RNA splicing, such as TRA2A/TRA2B, may represent a source of particularly strong synthetic lethalities and effective therapeutic targets for cancer." (PMID 40367120, 2025). "In this context, the Tra2b protein (the transformer 2 beta homolog) is particularly interesting as it is considered one of the most important splicing factors involved in RNA processing needed for both normal (e.g., brain development) and pathological (e.g., cancer) cell proliferation." (PMID 32545384, 2020). "Thus, inhibition of Tra2b or tNasp could probably be exploited to slow down or to abolish tumor cell growth as a new avenue of cancer therapy." (PMID 24586484, 2014). "How might upregulation of Tra2β affect the biology of cancer cells?" (PMID 23935626, 2013). "Here, we uncover a unique cancer vulnerability involving the paralogous splicing factors TRA2A and TRA2B." (PMID 40367120, 2025). "In ductal but not lobular tumors, significant inverse correlations were observed between the tumor levels of miR-10b and miR-30c and the mRNA levels of cancer-relevant target genes SRSF1, PIEZO1, MAPRE1, CDKN2A, TP-53 and TRA2B, as well as tumor grade." (PMID 30658617, 2019). "TRA2B or HNRNPA2B1 regulating repair of double strand breaks have elevated levels in various cancers and changed in levels by anti-cancer treatments as shown here." (PMID 23443080, 2012). "Experiments on two different cancer cell lines confirmed that TRA2B indeed regulated target gene expression and that this finding was not an incidental phenomenon in cancer cells." (PMID 37547760, 2023). "More generally, there is also evidence from cultured cancer cells that PEs in some splicing factor genes (although not TRA2B) enable the selection of new reading frames within mRNAs rather than targeting them for NMD, leading to the expression of alternative splicing factor isoforms." (PMID 41178187, 2025).
cancer (continued). "Moreover, a recent study reported that TRA2B is a proto-oncogene that may contribute to altering the expression of CYR61, which is related to cancer cell proliferation and apoptosis." (PMID 37547760, 2023). "HIPK3-T is not confirmed as a splicing target of Tra2β in cancer, since splicing of the HIPK3-T exon has only been observed thus far in human testis and has not been directly reported from cancer cells." (PMID 23935626, 2013).